SMAD7 (SMAD family member 7)
Diseases named in the same sentence as SMAD7 in open-access papers (continued):
Sharing a sentence is not in itself a finding about the gene and the disease.
liver disease (6 papers, 2011 to 2021). "Our results are consistent with a few recent studies pinpointing the functional role of Smad7 in liver diseases." (PMID 21386907, 2011). "In this regard, our model of liver-specific deletion of Smad7 can serve as a useful tool to comprehend the biological function of endogenous Smad7 in the liver as well as in liver diseases." (PMID 21386907, 2011). "The similar results could also be found in HCC, indicating the existence of circMTO1/miR‐17‐5p/Smad7 signalling axis in liver diseases." (PMID 31148365, 2019). "A few studies have emerged to reveal the role of Smad7 in liver diseases." (PMID 21386907, 2011). "The MSCs which overexpress a specific gene, such as Smad7 in this study, may achieve maximum clinical efficacy via targeting specific signalling pathways, which may shed a light on future therapeutics for end-stage liver disease." (PMID 32928296, 2020).
multiple sclerosis (6 papers, 2017 to 2024). A progressive autoimmune disorder affecting the central nervous system resulting in demyelination. "In addition, the recently described association of the intestinal Smad7 expression with multiple sclerosis in a murine model suggests a relevant role of SMAD7 in these autoimmune diseases." (PMID 31968593, 2020). "The expression of SMAD7 increased by a factor of 3.6 in multiple sclerosis (MS) patients after six months of VD supplementation." (PMID 37833895, 2023). "In intestinal biopsies from patients with multiple sclerosis, Smad7 was found to favor the expansion of intestinal CD4+ T cells toward an inflammatory phenotype and promote the migration of intestinal CD4+ T cells to the CNS." (PMID 34059951, 2021). "Expression of SMAD7 also decreases in the peripheral blood mononuclear cells of patients with multiple sclerosis." (PMID 32397546, 2020). "Microarray analysis revealed that the change in Smad7 expression following treatment with IVMP, in relapsing–remitting in patients with multiple sclerosis (in vivo), was significantly lower than that in CD4+ T cells from healthy donors (in vitro)." (PMID 34059951, 2021).
nasopharyngeal carcinoma (6 papers, 2017 to 2024). A carcinoma arising from the nasopharyngeal epithelium. "miR-324-3p regulates cell growth and apoptosis by targeting Mothers Against DPP Homolog 7 (SMAD7), and inhibits the migration and invasion of nasopharyngeal carcinoma by targeting wingless-type MMTV integration site 2B (WNT2B)." (PMID 31694199, 2019). "This microRNA was also involved in the restraint of cancer cell growth and apoptosis by targeting SMAD7 and WNT2B, and predicted radiosensitivity of nasopharyngeal carcinoma." (PMID 28977865, 2017).
ulcerative colitis (6 papers, 2013 to 2023). An inflammatory bowel disease involving the mucosal surface of the large intestine and rectum. "It is also important to note that SMAD7 is also a regulator of TGFβ signaling in immune cells that are linked to ulcerative colitis and inflammatory bowel syndrome, both risk factors for CRC." (PMID 25375357, 2014). "Since non-/former smokers have higher risk of ulcerative colitis compared with current smokers, our observation of a stronger SMAD7 SNP association among non-/former smokers would lend some support to the inflammation hypothesis." (PMID 23560096, 2013). "The final mechanism by which the tested drugs alleviate IAA-induced ulcerative colitis was by their anti-fibrotic effect manifested by the reduction of the TGF-β1/α-SMA axis and the enhancement of SMAD-7, effects that were reverted by the ulcerogenic inducer." (PMID 36386153, 2022).
celiac disease (5 papers, 2018 to 2023). An autoimmune genetic disorder with an unknown pattern of inheritance that primarily affects the digestive tract. "A recent study found significantly increased expression of SMAD7 (a regulatory molecule in the TGF-β pathway associated with increased inflammation) in duodenal biopsies of Pakistani children with EED compared to healthy controls and celiac disease patients from Italy43." (PMID 35017515, 2022). "In refractory celiac disease (CD), which is characterized by the persistence of malabsorption and villous atrophy despite a gluten-free diet and in the absence of other disorders, high SMAD7 levels were associated with defective TGF-β signaling and elevated production of inflammatory cytokines." (PMID 29415065, 2018). "The Smad7 protein, but not RNA, is over-expressed in the duodenum of RCD patients as compared to active and inactive celiac disease patients and normal controls, and this associates with reduced phosphorylation of Smad2/3." (PMID 33920230, 2021).
oral mucositis (5 papers, 2015 to 2023). Inflammation of the mucous membranes of any of the structures in the mouth. "Smad7 also plays several key functions in oral mucositis; for instance, Smad7 negatively regulates both TGF-β and NF-κB signaling, thereby inhibiting inflammation and pro-inflammatory cytokines so as to reduce mucositis formation." (PMID 34059951, 2021). "In oral mucositis, Smad7 can directly reduce DNA damage or promote DNA repair, using local short-term Tat-Smad7 to inhibit TGF-β-mediated growth arrest and apoptosis and TGF-β/NF-κB-mediated inflammation." (PMID 34059951, 2021). "Intriguingly, transgenic mice expressing high levels of Smad7 (K5.Smad7) in oral epithelia resulted more resistant to radiation-induced oral mucositis development than wild type mice." (PMID 33028357, 2020). "The major objective of this review is to evaluate the known functions of Smad7, with a particular focus on its molecular mechanisms and its function in blocking multiple pathological processes in oral mucositis." (PMID 25566830, 2015). "Smad7, the negative regulator of TGFβ signaling, inhibits both NF-κB and TGFβ activation and thus plays a pivotal role in the prevention and treatment of oral mucositis by attenuating growth inhibition, apoptosis, and inflammation while promoting epithelial migration." (PMID 25566830, 2015).
osteonecrosis (5 papers, 2021 to 2025). A none disease characterized by death of bone tissue due to a lack of blood supply. "Collectively, the miR-148a-3p/SMURF1/SMAD7/BCL2 axis contributes to maintaining osteoblast viability and bone integrity, thereby alleviating osteonecrosis of the femoral head." (PMID 41511311, 2025). "Furthermore, the stimulatory effect of miR-17-5p over the expression of COL1A1 was also described in patients with non-traumatic osteonecrosis, as a consequence of the inhibition of SMAD7." (PMID 37239902, 2023).
ovarian carcinoma (5 papers, 2018 to 2023). A malignant neoplasm originating from the surface ovarian epithelium. "HDAC1 induces the deacetylation and ubiquitination of SMAD7 required for the maintenance of the epithelial phenotype of CSCs in ovarian cancer, thereby reducing SMAD7 stability." (PMID 37394580, 2023).
rectal cancer (5 papers, 2019 to 2021). A primary or metastatic malignant neoplasm that affects the rectum. "The analysis included data from 243 rectal cancer patients and confirmed that the SNPs rs12953717 and rs4464148, located in an intron of SMAD7 on 18q21, were significantly associated with rectal cancer recurrence." (PMID 31052449, 2019). "A study investigating susceptibility loci, which could predict rectal cancer prognosis after surgery, confirmed that the rs12953717 and rs4464148 variants are significantly associated with rectal cancer recurrence and patients with lower Smad7 expression exhibit a longer disease-free survival." (PMID 33920230, 2021). "The genotype analysis of these SNPs of SMAD7 gene revealed that the CG genotype of rs2337106 (44± 55.0), (15±51.7) and TC genotype of rs6507874 (37± 46.2), (17±58.6) were the most prevalent genotypes in both colon and rectum cancer, respectively." (PMID 32190221, 2020). "In addition to SMAD7 (P = 0.0005) and SMAD3 (P = 0.0003), several other genes or genetic regions (CYP2R1, CHAF1A, CREBBP, IL10, SNPs identified in genome-wide association studies (GWAS) to be associated with IGF levels, IGFBP2/IGFBP5, IGFBP3, and C-MYC region) were associated with rectal cancer." (PMID 31434255, 2019).
scleroderma (5 papers, 2012 to 2019). Scleroderma is a rare autoimmune connective tissue disorder characterized by abnormal hardening of the skin and, sometimes, other organs. "Impairment of SMAD7 signaling has been associated with scleroderma fibroblasts." (PMID 29033951, 2017).
cervical cancer (4 papers, 2013 to 2024). A primary or metastatic malignant neoplasm involving the cervix. "Using cervical cancer cell lines and specimens, we validated that miR-519d was associated with Smad7 downregulation and tumor metastasis in cervical cancer." (PMID 27006642, 2016). "It was reported that Smad7 was rarely mutated in human cervical cancer tissues." (PMID 27006642, 2016). "NC, miR-519d inhibitor and Smad7 shRNA oligo were transfected independently or simultaneously into cervical cancer cells." (PMID 27006642, 2016). "In the next step, we analyzed the involvement of Smad7 in the tumor-promoting role of miR-519d in cervical cancer." (PMID 27006642, 2016). "Taken together, our findings conceivably validated that Smad7 potentially played an important role in miR-519d-mediated cervical cancer invasion and progression." (PMID 27006642, 2016). "Depletion of Smad7 by transfection of shSmad7 oligo significantly promote the proliferation of HeLa and SiHa cervical cancer cells compared with NC group." (PMID 27006642, 2016). "Depletion of Smad7 regained the migration and invasion of cervical cancer cells following miR-519d inhibition." (PMID 27006642, 2016). "Taken together, these findings implicated that miR-519d promoted the progression and metastasis of cervical cancer through targeting Smad7." (PMID 27006642, 2016). "Suppression of miR-519d augmented Smad7 expression, leading to attenuated capacity of cervical cancer invasion." (PMID 27006642, 2016). "And more notably, suppression of Smad7 remarkably restored the migration and invasion of miR-519d-depleted cervical cancer cells." (PMID 27006642, 2016). "However, the expression pattern and pathological significance of Smad7 in cervical cancer remains to be clarified." (PMID 27006642, 2016). "Furthermore, we analyzed the involvement of Smad7 in miR-519d-mediated cervical cancer migration and invasion." (PMID 27006642, 2016). "In summary, our current study showed that miR-519d-mediated downregulation of Smad7 might contribute to cervical cancer invasion and metastasis." (PMID 27006642, 2016). "Finally, we identified that Smad7 was a novel miR-519d target gene, and played a crucial role in miR-519d mediated tumor-facilitating effect in cervical cancer." (PMID 27006642, 2016). "Our findings implied that high expression of miR-519d may contribute to the development of cervical cancer through targeting Smad7, providing novel insight into the role of miRNAs in the regulation of cervical cancer metastasis." (PMID 27006642, 2016). "Our findings implicated that upregulated expression of miR-519d might contribute to cervical tumorigenesis via targeting Smad7, while depletion of Smad7 abrogated the influence of miR-519d on cervical cancer migration and invasion." (PMID 27006642, 2016). "Coinciding with this hypothesis, we found that miR-519d directly targeted Smad7 in cervical cancer cells." (PMID 27006642, 2016). "Additionally, we found that miR-519d directly targeted the mRNA of Smad7 to mediate the decay of Smad7 mRNA, thus facilitating the metastasis of cervical cancer." (PMID 27006642, 2016). "However, it remains unclear whether posttranscriptional regulation of Smad7 may contribute to the development of cervical cancer." (PMID 27006642, 2016). "Moreover, we identified Smad7 to be a novel target of miR-519d in cervical cancer cells." (PMID 27006642, 2016). "Smad7 is a critical inhibitor of TGF-β signaling pathway, which was reported to be expressed in tumor cells of numerous cancer types, including cervical cancer." (PMID 27006642, 2016). "Although no alterations in the Smad7 gene have been described in cervical cancer, we investigated if increased Smad7 levels could play a role in the progressive loss of growth inhibitory response to TGF-β1 that we observed as HKc/HPV16 progress to the HKc/DR stage." (PMID 24047375, 2013).
cervical cancer (continued). "In addition, the expression of Smad7, a potential target of miR-519d, was also examined between cervical cancer and adjacent non-tumorous tissues, which found that Smad7 was downregulated in cervical cancer samples, compared with non-tumorous tissues." (PMID 27006642, 2016).
Cirrhosis (4 papers, 2009 to 2021). A chronic disorder of the liver in which liver tissue becomes scarred and is partially replaced by regenerative nodules and fibrotic tissue resulting in loss of liver function. "After treatment with Smad7-MSCs, the expression of Smad7 was significantly increased in the recipient liver with cirrhosis." (PMID 32928296, 2020). "Some investigators have used gene therapy with an adenoviral vector containing Smad7 complementary DNA (cDNA) and a Chinese herbal medicine, to treat fibrosis and cirrhosis in different experimental models." (PMID 19878580, 2009).
glomerulosclerosis (4 papers, 2022 to 2024). A hardening of the kidney glomerulus caused by scarring of the blood vessels. "Activation of Smad2/3 promotes the secretion of ECM, leading to glomerular sclerosis and fibrosis, while Smad7 induces apoptosis of podocytes by blocking the activity of NF-kB." (PMID 37538798, 2023). "Among its components, Lei Gong Teng polyglucoside has been shown to alleviate glomerulosclerosis in rats with adriamycin nephropathy by regulating the expression of TGF-β1, Smad3, p-Smad2/3, and Smad7." (PMID 39687302, 2024).
lung adenocarcinoma (4 papers, 2010 to 2023). A carcinoma that arises from the lung and is characterized by the presence of malignant glandular epithelial cells. "Here, we found that SMAD7, a direct downstream transcriptional target and also a key antagonist of TGF-β signaling, is transcriptionally suppressed in lung adenocarcinoma (LAD) due to DNA hypermethylation." (PMID 37072414, 2023). "We stained the lung adenocarcinoma TMA with antibodies against an EMT marker (E-cadherin 1 (CDH1), molecules included in the signature (SMAD7, PLAUR), and immune checkpoint markers." (PMID 30783512, 2019).
Peritoneal Fibrosis (4 papers, 2015 to 2024). Disorder characterized by a wide range of structural changes in PERITONEUM, resulting from fibrogenic or inflammatory processes. "Increased Smad2/3 activation and decreased Smad7 expression is found in a peritoneal fibrosis model exposed to PD solution containing high concentrations of glucose in uremic rats." (PMID 39201294, 2024). "Overexpression of Smad7 by gene transfer inhibits Smad2/3 activation, reduces peritoneal fibrosis, and improves impaired peritoneal function in the model." (PMID 39201294, 2024). "It was discovered that EZH2 has a role in repressing Smad7 to enable activation of fibrotic genes in cardiac, kidney, and peritoneal fibrosis." (PMID 37476157, 2023). "We demonstrated that Akt modulates TGF-β1-induced MMT and peritoneal fibrosis in PD via downstream interactive signaling molecules, such as, Smurf2 and Smad7, and USP4 and TβR-1." (PMID 25885904, 2015). "Thus, inhibiting TGF-β or enhancing Smad7 expression likely represents an effective therapy for peritoneal fibrosis." (PMID 28873458, 2017). "Interestingly, transfer of Smad7 gene by ultrasound microbubble method into the peritoneum inhibits Smad2/3 activation, decreases α-SMA expression, and attenuates peritoneal fibrosis in a rat model of PD." (PMID 25885904, 2015). "Two inhibitors of EZH2 HMT activity, 3-Deazaneplanocin A (DZNep) and GSK126, can preserve Smad7 expression to significantly prevent UUO-induced kidney fibrosis, transverse aortic constriction surgery-induced cardiac fibrosis in mice, and a mouse model of peritoneal fibrosis." (PMID 37476157, 2023). "Thus, we hypothesized that activation of Akt by TGF-β1 increases Smurf2 expression which would inhibit Smad7, and thus Akt could participate in TGF-β1-induced MMT and peritoneal fibrosis in mice undergoing PD." (PMID 25885904, 2015).
schistosomiasis (4 papers, 2019 to 2024). An infectious disease caused by parasitic trematodes of the genus Schistosoma that colonize human blood vessels and release eggs that can cause granulomatous reactions leading to acute (swimmer's itch or acute schistosomiasis syndrome) or chronic disease. "Our published data showed that S. japonicum infection significantly upregulated miRNA-96 expression, promoting schistosomiasis HF in mice by suppressing Smad7." (PMID 39363237, 2024). "Gain- or loss-of-function experiments in vitro and in Malat1-KO mouse models in vivo revealed its suppressive effect on the progression of schistosomiasis HF through Malat1/miR-96/Smad7 axis." (PMID 39363237, 2024). "Elevated lncRNA Malat1 expression in infected HSCs reduces fibrosis via the Malat1/miR-96/Smad7 pathway, thus providing a novel therapeutic target for schistosomiasis HF." (PMID 39363237, 2024). "This study demonstrates that S. japonicum infection-induced downregulation of Malat1 expression contributes to schistosomiasis HF via the Malat1/miR-96/Smad7 axis." (PMID 39363237, 2024). "Taken together, these data revealed that in the infected mice, knockout of Malat1 gene upregulated miRNA-96 expression, leading to a reduction of Smad7 expression, indicating that the Malat1-mediated suppression of the schistosomiasis HF occurs through the Malat1/miRNA-96/Smad7 axis." (PMID 39363237, 2024). "Thus, we can summarize the mechanism as schistosome infection induces downregulation of Malat1 expression, increasing the miRNA-96 expression by reducing Malat1-mediated endogenous sponging, and elevated miRNA-96 promotes schistosomiasis HF by targeting Smad7." (PMID 39363237, 2024). "Therefore, we investigated whether the Malat1-mediated suppression of schistosomiasis HF occurs through the Malat1/miRNA-96/Smad7 axis." (PMID 39363237, 2024). "We further demonstrated this in the Malat1-KO infected mice, showing that Malat1 knockout significantly upregulated miRNA-96 expression, leading to reduced Smad7 expression and elevated expression of profibrogenic genes α-SMA, Col1α1 and Col3α1, resulting in a more severe schistosomiasis HF." (PMID 39363237, 2024).
squamous cell carcinoma (4 papers, 2008 to 2021). A carcinoma arising from squamous epithelial cells. "Smad7 cooperates with oncogenic Ras to cause malignant conversion in a mouse model for squamous cell carcinoma, which is associated with the blockade of normal differentiation." (PMID 18781153, 2008). "Human papilloma and squamous cell carcinoma (SCC) express elevated levels of Smad7 as compared to normal epidermis." (PMID 24317436, 2013). "When Smad7 was transduced together with HRAS, keratinocytes rapidly progressed to squamous cell carcinomas in vivo, whereas transduction with HRAS together with Smad6 or an empty vector control resulted in benign papillomas." (PMID 24047375, 2013).
adenoma (3 papers, 2013 to 2017). A neoplasm arising from the epithelium. "The SMAD7 rs12953717 was identified in the GWAS for both adenomas and cancers." (PMID 23472153, 2013). "SMAD7 expression is lower in cancers than adenomas irrespective of 18q copy number status makes a bystander effect unlikely and suggests a direct role for SMAD7 in carcinogenesis." (PMID 23472153, 2013).
autoimmune disease (3 papers, 2020 to 2024). A disorder resulting from loss of function or tissue destruction of an organ or multiple organs, arising from humoral or cellular immune responses of the individual to their own tissue constituents. "In this review, we aim to summarize the various biological functions of Smad7 in autoimmune diseases, inflammatory diseases, cancers, and kidney diseases, focusing on the molecular mechanisms of the transcriptional and posttranscriptional regulation of Smad7." (PMID 34059951, 2021).